FOXP3 (forkhead box P3)
Diseases named in the same sentence as FOXP3 in open-access papers (continued):
Sharing a sentence is not in itself a finding about the gene and the disease.
autoimmune disease (continued). "Human and mouse CD4+FoxP3+ T cells (Tregs) comprise non-redundant regulatory compartments which maintain self-tolerance and have been found to be of potential therapeutic usefulness in autoimmune disorders and transplants including allogeneic hematopoietic stem cell transplantation (allo-HSCT)." (PMID 35799783, 2022). "It has been shown that expression levels of Foxp3 and CD45RA in CD8+ CCR7+ Treg are lower in older individuals compared to young, and this may suggest a diminished suppressive capacity of these cells potentially contributing to the development of autoimmune diseases in the elderly." (PMID 33584708, 2020). "Treg cells are known to differentiate into IFN-γ- or IL-17-producing Treg cells, or to transdifferentiate into Foxp3-negative Th1, Th17 or Tfh cells, referred to as exTreg cells, under lymphopenic or inflammatory conditions in mice, and in patients with cancer, autoimmune disease or infections." (PMID 32471185, 2020). "Interestingly, these Treg cells suppress autoimmune diseases independent of Foxp3 expression." (PMID 29441062, 2018). "The reduced peripheral induction of FoxP3+ Treg cells does not hinder the protection against spontaneous or provoked encephalomyelitis in the Tg4 mouse, suggesting that thymic nTreg cells provide an important barrier to the development of this autoimmune disease." (PMID 23593464, 2013). "Although Tg4 FoxP3gfp mice do not show an increase in the incidence of spontaneous autoimmune disease, the impaired generation of iTreg cells that results from the modification of FoxP3 raised the question whether they display augmented susceptibility to induced EAE." (PMID 23593464, 2013). "Both Foxp3+ and Foxp3− Treg may play a pivotal role in the negative regulation of immune system function and inhibition of inflammation, as well as in the prevention of autoimmune diseases and graft rejection." (PMID 19924236, 2009). "In all these situations, the lack of survival signals will drive the majority of Foxp3+ Treg cells into apoptosis leading to a significant reduction in the number of Treg (CD4+CD25−Foxp3+) cells and to a reduced potential to suppress autoimmune diseases." (PMID 35563702, 2022). "Of note, expression of miR-10a is lowest in Tregs from animals prone to autoimmune disease, such as non-obese diabetic (NOD) mice, and in Tregs with unstable Foxp3 expression." (PMID 23818888, 2013). "These FoxP3+CD4+ Treg cell subsets are non-functional in male scurfy mice and boys with the multi-organ autoimmune disease immune-dysregulation polyendocrinopathy enteropathy X-linked syndrome (IPEX), due to loss-of-function mutations in the X-linked rodent Foxp3 and human FOXP3 genes, respectively." (PMID 25852682, 2015). "Moreover, we show that while CTLA-4, but not IL-10, plays a role in the induction of Foxp3 expression in naive CD4+ T cells, the latter is important for iTreg cell-mediated protection from autoimmune disease." (PMID 25238105, 2014). "We preferred this strategy, rather than generating a novel Foxp3-DTR transgenic line directly on the NOD genetic background, because adult DEREG mice on a non-autoimmune prone genetic background have been shown to be resistant to autoimmune diseases or scurfy-like symptoms after DT treatment." (PMID 34447385, 2021). "Our retinal βgal/BG2 TCR Tg/FoxP3-DTR model system is well suited for demonstrating the role of pTregs in tissue-specific immune privilege in that naive mice, whether expressing one or any combination of the transgenes, do not develop autoimmune disease." (PMID 25498509, 2014).
breast carcinoma (441 papers, 2008 to 2026). "And increased FoxP3 Treg infiltration is positively associated with decreased OS in cervical, kidney, gastric, liver, melanoma, and breast cancers." (PMID 40216744, 2025). "High FoxP3 Tregs infiltration in ER- breast cancer patients were associated with better outcomes, while it was associated with poor prognosis in ER+ patients with the same status." (PMID 40216744, 2025). "High numbers of FOXP3+ Tregs in tumors are generally associated with worse overall survival in breast cancer." (PMID 40563570, 2025). "Both Ep-CAMhi and CD24hi breast cancer were associated with indicators of immune evasion, including PD-L1 expression, and the infiltration of FOXP3+ and PD-1+ tumor-infiltrating lymphocytes (TIL)." (PMID 40943144, 2025). "Studies performed in different cohorts of breast cancer patients have shown that the presence of Foxp3+ cells is increased in high-grade tumors and is associated with increased risk of relapse and decreased survival." (PMID 38892447, 2024). "Clinically, the elevation of CD4+CD25+FOXP3+ Tregs in the peripheral blood has been found to be associated with a higher risk of tumor recurrence and a poor prognosis in breast cancer patients." (PMID 38177106, 2024). "Activin has been implicated in the promotion of a CD4+/Foxp3+ phenotype in a dose‐dependent manner in both malignant (breast cancer) and non‐cancerous disease models." (PMID 39248018, 2024). "As a result, the intratumoral ratio of CD8/FOXP3 cells decreased upon ICB, whereas a high CD8/FOXP3 ratio has been associated with improved survival in breast cancer patients." (PMID 37089449, 2023). "In the breast cancer microenvironment, FOXP3+ lymphocytes were strongly associated with both lower relapse-free survival (RFS) and OS." (PMID 37835488, 2023). "Our work aims to investigate Foxp3+ cells in 59 canine mammary tumors by immunohistochemistry and to evaluate associations with clinicopathological, immunohistochemical features, and overall survival (OS)." (PMID 36766393, 2023). "As expected, the majority of Tregs infiltrating breast cancer tumors are of thymic origin, which characteristically express Helios (a transcription factor associated with tTregs that promotes Foxp3 expression and stability)." (PMID 35472214, 2022). "In contrast, the presence of FOXP3-positive Tregs in breast cancer has been paradoxically reported to be associated with both reduced and improved survival." (PMID 35763240, 2022). "In breast cancer, FOXP3+ Tregs are a distinct population of T cells associated with more aggressive forms of breast cancer, including a higher risk of relapse and decrease in survival." (PMID 36387071, 2022). "In breast cancer, FOXP3 expression was associated with worse distant metastases-free survival, and the risk increased with increasing FOXP3 immunostaining intensity." (PMID 36010863, 2022). "With this in mind, we aimed to confirm the positive association between CCR4 and FOXP3 in other cohorts of breast cancer patients." (PMID 35222362, 2022). "CD4, CD25 T cells are associated with a poor prognosis in breast cancer and correlate with the expression of FOXP3, a tumor-promoting CD4 T cell, also termed regulatory T cells." (PMID 34638488, 2021). "Significant association of promoter methylation and its protein expression in patients with methylated FOXP3 promoter or FOXP3 Protein expression loss with various clinicopathological features of breast carcinoma." (PMID 34938323, 2021). "CD8+ T cells was reported to be associated with the outcome of breast cancer, Foxp3+ regulatory T cells (Treg cells) was significantly associated with poor survival of majority of solid tumors, including cervical, renal, melanomas, and breast cancers." (PMID 34930261, 2021). "The expression vectors encoding wild-type FOXP3 or empty vectors were transfected into MCF7 human breast cancer cells." (PMID 34768829, 2021).
breast carcinoma (continued). "Statistical association study of methylated FOXP3 gene with clinicopathological parameters of patients having breast carcinoma." (PMID 34938323, 2021). "The downregulation and many functional somatic mutations in the FOXP3 gene were usually found in human breast cancer samples." (PMID 34938323, 2021). "A high Foxp3+ Tregs infiltration is associated with poor recurrence-free survival in breast cancer patients (combined HR 1.58; 95% CI, 1.03 to 2.44; p < 0.0001)." (PMID 34885122, 2021). "Previous studies also reported that many SNPs in the FOXP3 gene had been associated with breast cancer." (PMID 34938323, 2021). "At the same time, we cannot forget that significant studies have suggested the positive association between FOXP3 expression and better survival in patients and the tumor-suppressive role of the FOXP3 gene in breast cancer." (PMID 34938323, 2021). "Metaplastic breast cancers were also significantly enriched for TILs expressing FOXP3, with FOXP3 positive intra-tumoural TILs (iTILs) associated with an adverse prognostic outcome (P = 0.0226)." (PMID 32939056, 2020). "FOXP3+ TIL are associated with poor prognosis in most cancers including breast cancer, lung cancer and pancreatic cancer, but in the case of colorectal or gastric cancer, FOXP3+ TIL correlate to improved clinical outcomes." (PMID 33013886, 2020). "Intriguingly, the converse is true for FOXP3, with FOXP3 positive iTILs associating with a much poorer breast cancer-specific survival." (PMID 32939056, 2020). "We also investigated the CD4/CD8, CD8/FOXP3, and FOXP3/CD4 ratio because there have been several studies that reported the CD8/FOXP3 ratio in breast cancer." (PMID 32222891, 2020). "High infiltration of FoxP3+ Tregs has been reported to be associated with unfavorable outcome of multiple malignancies including breast cancer, ovarian carcinoma, lung cancer, hepatocellular carcinoma, and gastric cancer." (PMID 31138162, 2019). "Results also showed that as FOXP3 staining intensity increased, the survival risk of breast cancer patients also increased." (PMID 31852159, 2019). "FoxP3+ Tregs are associated with short survival in the majority of solid tumors including melanomas, cervical, renal, and breast cancers." (PMID 31639056, 2019). "Our genome-wide chromatin immunoprecipitation (Chip-on-chip) studies in human Treg cells and other studies in breast cancer cells identified a large number of potential FOXP3 target genes including loci encoding microRNAs (miRs)." (PMID 29963231, 2018). "In ER- breast cancer, tumor-infiltrating FOXP3+ lymphocytes and CCL5 expression were associated to a good outcome." (PMID 29559701, 2018). "We then examined the consequences of the regulation of ZEB2 by FOXP3 and miR-155 on sentinel marker genes implicated in the invasive and migratory potential of human breast cancer cells." (PMID 29963231, 2018). "Consistently, immunosuppressive function of specific Tregs located in the TLS has been suggested in KP mice and in breast cancer patients with TLS in whom FoxP3/T cells were shown to be the only marker associated with poor prognosis." (PMID 30038899, 2018). "Our previous study showed that the reduction in the expression of nuclear FOXP3 protein was significantly associated with tumor progression in breast cancer patients." (PMID 29549328, 2018). "For example, a germline mutation of FOXP3 results in a high rate of spontaneous breast cancer in mice." (PMID 30011797, 2018). "Forkhead box P3 (FOXP3), an X-linked tumor suppressor gene, plays an important role in breast cancer." (PMID 29970908, 2018). "Previous studies have revealed that a high density of FOXP3+ TIL is associated with worse OS in breast cancer, hepatocellular carcinoma, and ovarian cancer." (PMID 30153850, 2018). "Recently, it has been discovered that abnormal Foxp3 expression is associated with a series of cancers, such as prostate, ovary, and breast cancer." (PMID 28923073, 2017).
breast carcinoma (continued). "To avoid the potential effect of FOXP3+ TILs, we selected the CD25low tumors, indicative of few FOXP3+ TILs, to assess the association between expression of FOXP3 and miR-200 s in the TCGA breast cancers." (PMID 28637482, 2017). "In our BALB/c mouse tumor model using syngenic D2F2 mammary cancer cells as a model of any type of cancer, acrolein exposure resulted in enhanced tumor growth associated with an accumulation of intratumoral Foxp3+ cells." (PMID 28332605, 2017). "Genetic analysis of some diseases like psoriasis and breast cancer showed significant association with the single nucleotide polymorphisms (SNP) rs3761548 (−3279 C/A) and rs2232365 (−924 A/G) of FOXP3 gene." (PMID 27830498, 2016). "In most cancers, including breast cancer, infiltrating of FOXP3+ regulatory TILs have been reported to be associated with worse clinical outcome." (PMID 27566250, 2016). "In our meta-analysis, 15 eligible articles were included which evaluated the association between FOXP3+ TILs level and prognosis of breast cancer." (PMID 27566250, 2016). "Foxp3 is an X-linked tumor suppressor gene expressed in the normal mammary gland, but downregulated, mutated or cytoplasmically localized in mammary tumor cells." (PMID 26735887, 2016). "Our meta-analysis demonstrates that the presence of high levels of FOXP3+ TILs is associated with prognosis for breast cancer patients and predicts lymph node metastasis, hormone receptor and HER-2 status." (PMID 26475790, 2015). "In breast cancer, the complete response of breast carcinoma to neoadjuvant chemotherapy was associated with a disappearance of tumor-infiltrating Foxp3+ Treg cells." (PMID 25352158, 2015). "FoxP3+ Tregs were strongly associated with reduced lower OS rate in ER+ breast cancer cases, with a pooled OR of 1.50 (95% CI 1.17 to 1.93), but was associated with a improved survival in ER- cases, with a pooled OR of 0.45 (95% CI 0.31 to 0.65)." (PMID 26462617, 2015). "In some tumor types including hepatocellular carcinoma and breast cancer, high levels of intratumoral Foxp3+CD4+ T cells have been associated with bad prognosis." (PMID 26604855, 2015). "In the stratified analysis according to ER status, we found high numbers of FoxP3+ Tregs was associated with a favorable outcome in ER- breast cancer, but was associated with poor prognosis in ER+ breast cancer." (PMID 26462617, 2015). "Subsequent studies reported that breast cancer cells expressed Foxp3, and that Foxp3 positivity was associated with poor prognosis." (PMID 25779374, 2015). "Our pooled analysis of the 13 studies with a total of 5,167 patients suggested high FoxP3+ Tregs infiltration was significantly associated with decreased OS in breast cancer." (PMID 26462617, 2015). "In conclusion, our meta-analysis demonstrates that the presence of high levels of FOXP3+ TILs is associated with prognosis for breast cancer patients and predicts lymph node metastasis, hormone receptor and HER-2 status." (PMID 26475790, 2015). "Higher CD8+/Foxp3+ was authenticated to be associated with favorable outcome in both breast cancer and ovarian cancer." (PMID 24276989, 2014). "Foxp3-positive cell/TIL ratio was associated with RFS in breast cancer (p = 0.0368; HR 0.2974; 95 % CI 0.09525–0.9286)." (PMID 24562936, 2014). "FOXP3+ TILs were assessed by immunohistochemistry on tissue microarrays constructed from a well-defined cohort of 3,992 breast cancer patients linked to detailed demographic, biomarker, treatment and outcome data." (PMID 25193543, 2014). "Our study indicates that the infiltration of FOXP3+ lymphocytes not only has distinctive prognostic associations within different subtypes of breast cancer, but also interacts with cytotoxic T-cell infiltrates in their association with patient survival." (PMID 25193543, 2014). "Immunosuppressive Foxp3-positive Tregs have been linked to poor response to chemotherapy and poor prognosis among breast cancer patients." (PMID 24562936, 2014).
breast carcinoma (continued). "To confirm the prognosis of FOXP3+ TILs in breast cancer, we also evaluated the association of FOXP3+ iTIL with relapse-free survival; results were very similar to those using breast cancer-specific survival as the outcome." (PMID 25193543, 2014). "Although we believe that the measurement of FOXP3+ TILs and the evaluation of the association of FOXP3+ TILs with breast cancer patient survival are reliable and form a consistent picture with other reports, there are some limitations in this study." (PMID 25193543, 2014). "In a previous study, Foxp3 expression in primary breast cancer was associated with a worse overall survival probability, and this risk was correlated with increased Foxp3 immunostaining." (PMID 24179494, 2013). "It has previously been reported that high levels of FOXP3 protein expression are associated with a poor prognosis and low survival of breast cancer." (PMID 23759077, 2013). "Conflicting prognostic values for tumor-expressed FOXP3 were reported in immunohistochemical studies of breast cancer, in which FOXP3 was associated with poor, as well as with favorable prognosis." (PMID 24649219, 2013). "Previous studies indicated that Foxp3 is expressed in breast cancer cells, and that the expression level was associated with patient survival." (PMID 24179494, 2013). "A paradoxical positive association was found between favorable outcome and expression of FOXP3, previously reported to be associated with worse overall survival of patients with breast cancer." (PMID 23758773, 2013). "Downstream FOXP3, we found that down-regulation of p21, a protein involved in stem cell differentiation and apoptosis, is associated with FOXP3 down-regulation, as recently reported in breast cancer samples." (PMID 23888189, 2012). "Our data clearly document that, although numbers of FOXP3+ lymphocyte infiltration in ductal breast cancer are significantly associated with unfavourable clinico-pathological features, this marker alone does not appear to represent a prognostic marker." (PMID 22471961, 2012). "For instance, one TReQTL in the CEU population is associated with the DSTs of the X-linked breast cancer suppressor gene Foxp3 (T04280) transfactor." (PMID 22479588, 2012). "In breast cancer, it has been demonstrated that pathologic complete response to neoadjuvant chemotherapy of breast carcinoma is associated with the disappearance of tumor-infiltrating Foxp3+ regulatory T cells." (PMID 22693525, 2012). "One TReQTL SNP (rs3790904) in CEU maps to Lphn2 and is associated (nominal p-value = 8.1×10−7) with the targets of the X-linked breast cancer suppressor Foxp3." (PMID 22479588, 2012). "Previous publications have linked Foxp3+ TILs to a worse prognosis in e.g. ovarian and breast cancer." (PMID 22701698, 2012). "In conclusion, our study shows that Foxp3+ cells are associated with more advanced disease in breast cancer, a finding that is proving to be true in many other cancers." (PMID 19604349, 2009). "We have previously demonstrated the association of B7-H1-expressing T infiltrating lymphocytes (TIL) with high-risk breast cancer patients while other studies reported the involvement of FOXP3+ Tregs as a bad prognostic factor in breast tumors." (PMID 18294387, 2008). "Similarly, CXCR5+FoxP3+ follicular regulatory T cells have been positively associated with LDH levels in breast cancer (BC)." (PMID 40091778, 2025). "Regardless of the presence or absence of HER‐2 amplification, deletion, functionally important somatic mutations, and downregulation of the FOXP3 gene were frequently observed in human breast cancer samples and significantly linked with HER‐2/ErbB2 overexpression." (PMID 38827026, 2024). "It remains open as to whether PD-1+ TILs and FOXP3+ TILs are linked with a higher or lower response to chemotherapeutics used in the neoadjuvant treatment of breast cancer." (PMID 37835488, 2023).